DGKQ (diacylglycerol kinase theta)
Description:
Diacylglycerol kinase that converts diacylglycerol/DAG into phosphatidic acid/phosphatidate/PA and regulates the respective levels of these two bioactive lipids. Thereby, acts as a central switch between the signaling pathways activated by these second messengers with different cellular targets and opposite effects in numerous biological processes. Within the adrenocorticotropic hormone signaling pathway, produces phosphatidic acid which in turn activates NR5A1 and subsequent steroidogenic gene transcription. Also functions downstream of the nerve growth factor signaling pathway being specifically activated in the nucleus by the growth factor (By similarity). Through its diacylglycerol activity also regulates synaptic vesicle endocytosis.
Synonyms: DAGK4; DAGK; DAGK7
Tractability: Antibody: UniProt places it where antibodies can reach, with high confidence; its Gene Ontology location is reachable by antibodies, with high confidence. PROTAC: ubiquitination databases record sites on it; its protein half-life has been measured.
Gene: Protein-coding gene on chromosome 4 (958,884 to 986,895, reverse strand). Ensembl gene ENSG00000145214.
Subcellular location: Cytoplasm; Cytoplasm, cytosol; Cell membrane; Synapse; Cytoplasm, cytoskeleton; Nucleus; Nucleus speckle; Nucleus matrix
Subcellular location (Human Protein Atlas): Nucleoli
Pathways (Reactome):
Hemostasis: Effects of PIP2 hydrolysis
Gene Ontology:
Molecular function: ATP-dependent diacylglycerol kinase activity; diacylglycerol-dependent serine/threonine kinase activity; DNA-binding transcription factor binding; kinase binding; phospholipase binding; protein binding; receptor tyrosine kinase binding; transmembrane receptor protein tyrosine kinase activator activity; alkylglycerol kinase activity; kinase activity
Biological process: adenylate cyclase-activating G protein-coupled receptor signaling pathway; cellular response to bile acid; diacylglycerol metabolic process; epidermal growth factor receptor signaling pathway; G protein-coupled receptor signaling pathway; glycerolipid metabolic process; lipid phosphorylation; negative regulation of gene expression; phosphatidic acid biosynthetic process; phospholipase C-activating G protein-coupled receptor signaling pathway; positive regulation of gene expression; positive regulation of protein kinase C signaling; regulation of cholesterol metabolic process; regulation of cortisol biosynthetic process; regulation of gluconeogenesis; regulation of progesterone biosynthetic process; regulation of TORC1 signaling; regulation of transcription by RNA polymerase II; response to cAMP; thrombin-activated receptor signaling pathway; intracellular signal transduction; platelet activation; regulation of synaptic vesicle endocytosis; signal transduction
Cellular component: cytoplasm; cytoskeleton; cytosol; endosome; nuclear speck; nucleolus; nucleus; plasma membrane; vesicle membrane; membrane; nuclear matrix; synapse; glutamatergic synapse; postsynapse; presynapse
Genetic constraint (gnomAD): Loss-of-function variants: 96 observed, 87.92 expected, observed/expected ratio (o/e) 1.09, 90% interval 0.93 to 1.29. The synonymous counts are far from expectation, so gnomAD's model fits this gene poorly and the ratio says little. Missense variants: 1,454 observed, 1,205.1 expected, observed/expected ratio (o/e) 1.21, 90% interval 1.15 to 1.26. Synonymous variants: 728 observed, 533.25 expected, observed/expected ratio (o/e) 1.37, 90% interval 1.28 to 1.45.
Homologues: Orthologues: chimpanzee DGKQ (96% identical), macaque DGKQ (96% identical), guinea pig DGKQ (82% identical), pig DGKQ (81% identical), rat Dgkq (81% identical), mouse Dgkq (81% identical), dog DGKQ (80% identical), tropical clawed frog dgkq (63% identical), Drosophila melanogaster CG31140 (40% identical), Caenorhabditis elegans dgk-1 (37% identical). Paralogues in human: DGKD (24% identical), DGKH (24% identical), DGKB (22% identical), DGKK (22% identical), DGKG (22% identical), DGKA (20% identical), DGKE (20% identical), DGKI (19% identical), DGKZ (19% identical).
Diseases named in the same sentence as DGKQ in open-access papers:
DGKQ is named in the same sentence as 18 diseases in open-access papers, as found by Europe PMC text mining. Sharing a sentence is not in itself a finding about the gene and the disease. The quoted sentences say what the papers report.
Parkinson disease (7 papers, 2012 to 2023). A progressive degenerative disorder of the central nervous system characterized by loss of dopamine producing neurons in the substantia nigra and the presence of Lewy bodies in the substantia nigra and locus coeruleus. "A GWAS of Parkinson’s disease has identified the TMEM175/GAK/DGKQ region at chromosome 4p16.3 as a significant risk locus of this disease." (PMID 37238672, 2023). "The association of single nucleotide polymorphisms (SNPs) in the GAK/DGKQ locus on chromosome 4 with Parkinson’s disease raised the possibility that TMEM175 gene in this region has pathophysiological significance in the neurodegenerative disorder." (PMID 34638858, 2021). "The TMEM175/GAK/DGKQ locus was the third strongest risk locus in a GWA study of Parkinson’s disease and has been described as a potential drug target." (PMID 34745218, 2021).
acute monocytic leukemia (1 paper, 2023). Acute monoblastic leukemia (AML-M5), is one of the most common subtypes of acute myeloid leukemia (AML) that is either comprised of more than 80% of monoblasts (AML-M5a) or 30-80% monoblasts with (pro)monocytic differentiation (AML-M5b). "DGKH consistently showed the lowest expression except in acute monocytic leukemia (AMOL), while DGKZ, DGKD, DGKQ and DGKA exhibited the highest expression levels." (PMID 37509516, 2023).
breast carcinoma (1 paper, 2025). "Of the 8 candidate MD-SNP that were associated with both mammographic density and breast cancer risk in this Asian study, one (rs3806759) showed significant associations with the expression of PCGF3 in breast tissue and DGKQ in subcutaneous adipose tissue." (PMID 41272850, 2025).
inclusion body myositis (1 paper, 2023). A slowly progressive degenerative inflammatory disorder of skeletal muscles characterized by late onset weakness of specific muscles and distinctive histopathological features. "We identified more significant associations than those previously reported in IIM for STAT4 and DGKQ in the total cohort, for NAB1 and FAM167A‐BLK loci in PM, and for CCR5 in inclusion body myositis." (PMID 36580032, 2023).
leukemia (1 paper, 2016). A malignant (clonal) hematologic disorder, involving hematopoietic stem cells and characterized by the presence of primitive or atypical myeloid or lymphoid cells in the bone marrow and the blood. "Furthermore, we confirmed the overexpressed PIK3R5, DGKQ and TNFSF9, which are crucial components of kinase pathways involved in leukemia and lymphoma, in manipulated Jurkat samples." (PMID 27681508, 2016).
osteopetrosis (1 paper, 2024). Osteopetrosis, also known as marble bone disease, is a descriptive term that refers to a group of rare, heritable disorders of the skeleton characterized by increased bone density on radiographs. "Therefore, we speculate that DGKQ and DGKZ may be involved in the pathogenesis of osteopetrosis by regulating the level of DAG." (PMID 40018371, 2024).
rheumatic diseases (1 paper, 2023). "A recent genome‐wide meta‐analysis of 4 seropositive rheumatic diseases revealed several novel loci, for example, NAB1, DGKQ, and YDJC, where IIM contributed to the association." (PMID 36580032, 2023).
type 1 diabetes (1 paper, 2022). "Interestingly, a recent integrative analysis of genetic association, functional genomics data and protein–protein networks identified DGKQ as a potential novel type 1 diabetes therapeutic gene target along with other novel and known targets, e.g., IL2RA, IL6ST, IL6R and TYK2." (PMID 35142878, 2022).
tumor (4 papers, 2019 to 2024). "Using healthy donor CD34+ cells as a reference, we detected overexpression of DGKA, DGKG, DGKD and DGKQ in tumor samples, while DGKH and DGKZ were unchanged." (PMID 37509516, 2023).
immune disease (1 paper, 2025). "For DGKQ, IL6ST and ANKRD55, decreased expression correlated with reduced immune disease risk, and increased expression with higher risk." (PMID 41361473, 2025).
movement disorder (1 paper, 2017). Neurological conditions resulting in abnormal voluntary or involuntary movement, which may impact the speed, fluency, quality and ease of movement. "Other genes, such as GAK, HTT, TMEM175, FAM193A, and DGKQ, were mainly related to movement disorders (adjusted p-value = 0.0001) and basal ganglia disease (adjusted p-value = 3.73e-05)." (PMID 28118382, 2017).
DGKQ also shares sentences with these, for which no sentence is quoted: asthma (1 paper); cerebral malaria (1); diabetes mellitus (1); Insulin resistance (1); lymphoma (1); Obesity (1); Parkinsonism (1).